LNCMB3 (lncRNA MYC regulated medulloblastoma associated 3)
Gene: Long non-coding RNA gene on chromosome 10 (120,984,942 to 120,996,775, reverse strand). Ensembl gene ENSG00000278484.
Diseases named in the same sentence as LNCMB3 in open-access papers:
LNCMB3 is named in the same sentence as 2 diseases in open-access papers, as found by Europe PMC text mining. Sharing a sentence is not in itself a finding about the gene and the disease. The quoted sentences say what the papers report.
cancer (1 paper, 2025). A tumor composed of atypical neoplastic, often pleomorphic cells that invade other tissues. "Among the top ontological annotations, GO revealed pathways such as “PIK3-Akt signalling”, associated to chemosensitivity in various cancers, including MB, and “MAPK signalling”, potentially reflecting apoptosis-induced DNA damage following lncMB3 KD." (PMID 41198629, 2025). "Targeting lncMB3 affects the TGF-β pathway, enhances apoptosis, and boosts chemotherapeutic efficiency in cancer cell lines." (PMID 41198629, 2025). "Our findings suggest that functional RNA-RNA interactions between coding and non-coding molecules—an emerging theme in cancer regulation—upregulate HMGN5 protein levels, explaining why HMGN5 RNA interference phenocopies lncMB3 targeting effects." (PMID 41198629, 2025). "However, HMGN5 protein levels dropped by ∼80% upon lncMB3 KD, consistently with HMGN5 recognised oncogenic activity in various cancers." (PMID 41198629, 2025). "A decrease in cancer cell survival was also observed, compared to DDP treatment alone, consistent with earlier data, indicating that HFt-based NPs are effective for lncMB3 targeting and sensitising G3 MB cells to anticancer drugs." (PMID 41198629, 2025).
tumour (1 paper, 2025). "LncMB3 is upregulated in G3 MB cell lines and primary tumours, playing a pivotal role in cell death evasion in vitro." (PMID 41198629, 2025).